MIEN1 (migration and invasion enhancer 1)
Diseases named in the same sentence as MIEN1 in open-access papers (continued):
Sharing a sentence is not in itself a finding about the gene and the disease.
prostate carcinoma (continued). "Rajendiran and colleagues found that miR-940 was highly expressed in normal tissues compared with tumors, and miR-940 inhibited migratory and invasive potential of prostate cancer cells and increased E-cadherin expression by regulating MIEN1." (PMID 26317898, 2015). "MIEN1 plays a role in prostate cancer migration and invasion through enhancement of filopodia formation by facilitating actin cytoskeletal rearrangement and by up-regulating the Akt dependent NF-κB target genes." (PMID 25406943, 2014). "MIEN1 is abundantly expressed in different stages and grades of prostate cancer phenotypes when compared to normal cells and tissues." (PMID 25406943, 2014). "In various androgen dependent and castration-resistant prostate cancer cells, both MIEN1 mRNA and protein are highly expressed compared to the immortalized normal cells of the prostate." (PMID 25406943, 2014). "This study is the first to identify miR-940 as a novel regulator of MIEN1, a molecule involved in prostate cancer progression." (PMID 25406943, 2014). "MIEN1 has recently been identified as an important gene within the 17q12 amplicon in various cancers including prostate cancer." (PMID 23468608, 2013). "Previous reports showed that MIEN1 expression is highly related clinically to breast and prostate cancer." (PMID 23284973, 2012). "Accordingly, the modulation of Akt signaling in the gene expressions of NDRG1 and IL-6 may account for the functions of MIEN1 in cell proliferation, invasion, and tumorigenesis in prostate carcinoma cells." (PMID 31581708, 2019). "Overexpression of MIEN1 may contribute to cell proliferation, migration, invasion, tumorigenesis, and cisplatin resistance in prostate carcinoma cells." (PMID 31581708, 2019). "Meanwhile, it was found that a novel miRNA, has-miR-940 (miR-940), reduced the anchorage-independent development capacity and enhanced mesenchymal-to-epithelial transition via the blockage of MIEN1 expression by inhibiting the migratory and invasive potential of prostate carcinoma cells." (PMID 31581708, 2019). "Although MIEN1 is regarded as a novel gene involved in prostate cancer progression by enhancing cell migration and invasion, the relative functional significance and regulatory mechanisms of MIEN1 remain largely unknown." (PMID 31581708, 2019). "Our lab has previously demonstrated that MIEN1 enhances the migration and invasion of prostate cancer cells by activating the Akt/NF-κB pathway which leads to an increase in certain proteases and angiogenic factors, and by altering actin cytoskeleton structures (propelling cellular movement)." (PMID 27589566, 2016). "Moreover, miR-940 was shown to suppress progression of prostate cancer and pancreatic ductal adenocarcinoma by suppressing Migration and invasion enhancer 1 (MIEN1) and MyD88, respectively." (PMID 26317898, 2015). "Hence, we are the first to report that miR-940 inhibits prostate cancer migration and invasion, at least in part via MIEN1 along with other probable targets." (PMID 25406943, 2014). "Previous studies indicate that MIEN1 plays an important role in prostate cancer progression." (PMID 25406943, 2014). "The results of this study revealed that the levels of MIEN1 protein and mRNA in prostate carcinoma cells (LNCaP, PC-3, and DU145) were higher than those in normal prostate (PZ-HPV-7 and CA-HPV-10) cells." (PMID 31581708, 2019). "The role of MIEN1 expression affecting apoptosis in prostate cancer cells has not yet been determined." (PMID 31552186, 2019). "However, the roles of MIEN1 in prostate cancer have not yet been clearly addressed." (PMID 31581708, 2019). "The prostate carcinoma cells (LNCaP, PC-3, and DU145) expressed higher levels of MIEN1 than did the normal or non-metastatic prostate cells (PZ-HPV-7 and CA-HPV-10)." (PMID 31581708, 2019).
prostate carcinoma (continued). "It has been suggested that both IL-6 and NDRG1 are modulated by Akt signal pathways; however, no report has yet studied the correlations among MIEN1, Akt, IL-6, and NDRG1 in human prostate cancer." (PMID 31581708, 2019).
breast tumor (5 papers, 2012 to 2021). "Our data reveals a novel mechanism whereby MIEN1 promotes actin reorganization and subsequently induces breast tumor cell migration through cofilin activation." (PMID 27462783, 2016). "Our study has now deciphered a novel regulatory network governing the vicious process of breast tumor cell invasion-metastasis, and findings suggest MIEN1-AnxA2 as prospective targets to counter the deadly disease." (PMID 26272794, 2015). "Our data show that the presence and interaction of both MIEN1 and AnxA2 in breast tumors are crucial drivers of cell motility." (PMID 26272794, 2015). "Clinically, MIEN1 is predominantly overexpressed in Her-2 and luminal B subtypes of breast tumors, and its increased expression correlates with poor disease free survival." (PMID 26272794, 2015). "Previous studies indicated that Syk kinase potentiates MIEN1 dependent signaling in breast tumor cells." (PMID 26272794, 2015). "Taken together, these data indicate that co-expression of both AnxA2 and MIEN1 enhance plasmin generation and lead to an increase in breast tumor cell migration and invasion which in turn drive the metastatic process." (PMID 26272794, 2015). "Migration and invasion enhancer 1 (MIEN1) is a novel gene found to be abundantly expressed in breast tumor tissues and functions as a critical regulator of tumor cell migration and invasion to promote systemic metastases." (PMID 26272794, 2015). "Migration and invasion enhancer 1 (MIEN1), previously named C35/C17orf37, is a novel gene identified by representational difference analysis of breast tumor and normal cells." (PMID 23284973, 2012). "Our data provide evidence that MIEN1 interaction with AnxA2 enhances Y23 phosphorylation of AnxA2 and subsequent translocation of the protein to the cell surface leads to increased plasmin levels which support breast tumor cell motility." (PMID 26272794, 2015). "Hence, validating the role of MIEN1 might indirectly be important in preventing breast tumor metastases." (PMID 27462783, 2016). "Hence, targeting MIEN1 might represent a promising means to prevent breast tumor metastasis." (PMID 27462783, 2016). "Migration and invasion enhancer 1 (MIEN1), previously known as C35, C17orf37, MGC14832, RDX12, ORB3 and XTP4, was first reported to be highly expressed in human breast tumors and its expression was shown to persist from early events in tumorigenesis to late stages of the disease." (PMID 27462783, 2016).
ovarian carcinoma (5 papers, 2019 to 2020). A malignant neoplasm originating from the surface ovarian epithelium. "Functional significance of the discovered targets in relation to ovarian cancer is discussed, with special focus on MIEN1 and NOP53." (PMID 32867128, 2020). "There is a pressing need to design in-depth studies to determine the role of MIEN1 in pathophysiology of ovarian cancer in relation to metastasis." (PMID 31552186, 2019). "Another study reported that MIEN1, potassium calcium-activated channel subfamily N member 3 (KCNN3), and drug resistance in ovarian cancer are significantly associated with each other." (PMID 35582722, 2019). "MIEN1 and DNp73 interaction induces chemo-resistance in ovarian cancer." (PMID 35582722, 2019). "High levels of MIEN1 are involved in ΔNp73-mediated cisplatin drug resistance in ovarian cancer." (PMID 31552186, 2019). "Most studies on MIEN1 have focused on migration and invasion; however, one study suggested that MIEN1 might cooperate with ΔNp73 to enhance cell proliferation and contribute to cisplatin resistance in ovarian cancer cells." (PMID 31581708, 2019). "We have experimentally probed that HMGB1, HMGB2 and two of their partners, MIEN1 and NOP53 are also involved in the response of ovarian cancer cells to several drugs used in chemotherapy against EOC." (PMID 32867128, 2020). "With these precedents we decided to investigate the role of HMGB1, HMGB2, MIEN1 and NOP53 in cell viability as well as in response and sensitivity to drugs currently used in ovarian cancer therapy." (PMID 32867128, 2020). "Expression changes of HMGB1, HMGB2, MIEN1 and NOP53 genes have been evaluated in response to drugs usually employed in ovarian cancer treatments: bevacizumab, olaparib, paclitaxel or carboplatin." (PMID 32867128, 2020). "HMGB1 and HMGB2 genes were silenced in SKOV-3 and PEO1 EOC cell lines and levels of mRNA from 4 detected interacting partners of HMGB1 or HMGB2 in ovary cancer, COMMD1, MIEN1, NOP53 and ZNF428, were analyzed by qRT-PCR as explained in Materials and Methods." (PMID 32867128, 2020). "The structure of MIEN1 and their emerging functions in relation to cancer have been recently reviewed, although the role of MIEN1 in pathophysiology of ovarian cancer had not been previously explored in depth." (PMID 32867128, 2020). "Interestingly, we have shown in our study that HMGB1, HMGB2 and their EOC-HMGB-interactome partners MIEN1 and NOP53 are involved in the response to carboplatin, or drugs nowadays used in ovarian cancer treatment, such as bevacizumab, olaparib and paclitaxel." (PMID 32867128, 2020). "We tested the effect of four compounds, used in ovary-cancer therapy in the expression of the genes HMGB1, HMGB2, MIEN1 and NOP53 in cultured cancerous SKOV-3 cells and in non-cancerous IOSE-80 ovarian cells." (PMID 32867128, 2020).
non-small cell lung carcinoma (3 papers, 2019 to 2024). A group of at least three distinct histological types of lung cancer, including non-small cell squamous cell carcinoma, adenocarcinoma, and large cell carcinoma. "SYVN1 promotes non-small cell lung cancer metastasis by blocking autophagy-mediated MIEN1 degradation." (PMID 38679705, 2024). "miR-26b decreased MIEN1 levels in non-small-cell lung cancer cells, which downregulated the metastasis activity via the NF-κB/MMP-9/VEGF (vascular endothelial growth factor) pathways." (PMID 31581708, 2019). "MIEN1 is overexpressed in several human cancers including breast, prostate, colorectal, gastric, ovarian, squamous cell carcinoma and non-small cell lung cancer (NSCLC), therefore playing an important role in biological processes underlying tumor metastasis." (PMID 31552186, 2019).
bladder cancer (2 papers, 2017). "MIR-940 levels were found to be the highest in invasive and advanced bladder cancer and has previously been found to inhibit the migratory and invasive potential of cells and increase E-cadherin expression by regulating MIEN1." (PMID 28589857, 2017). "Genes co-amplified with ERBB2 (GRB7, MIEN1, PGAP3, and STARD3) exhibited the highest amplification frequency in esophageal cancer, followed by stomach, breast, uterine, and bladder cancer." (PMID 29190909, 2017).
prostate tumors (2 papers, 2014 to 2019). "The study established the role of MIEN1 overexpression with migration and invasion of prostate tumor cells mediated via Akt/NF-kB signaling and activation of downstream effector proteins." (PMID 31552186, 2019). "Additionally, to determine if miR-940 levels vary in benign prostatic hyperplasia (BPH) and metastatic prostate tumors (Mets), we performed in situ hybridization and immunohistochemistry and quantified the staining intensities of miR-940 as well as MIEN1 in these tissues." (PMID 25406943, 2014). "Studies indicate that MIEN1 overexpression is linked to genomic amplification of the ERBB2 locus, since its sufficient expression is noted in the ERBB2 nonamplified breast and prostate tumors, suggesting that MIEN1 might have an independent functional promoter." (PMID 31552186, 2019).
adenoma (1 paper, 2025). A neoplasm arising from the epithelium. "Immunofluorescence analysis confirmed co-localization of MIEN1 with CD66b+ neutrophils, with a progressive increase in MIEN1+ neutrophil infiltration observed from normal mucosa to adenoma and carcinoma tissues." (PMID 40959269, 2025).
brain tumors (1 paper, 2019). "However, additional studies are needed to establish the involvement of MIEN1 in other types of cancers such as brain tumors, melanoma, hematological malignancies and other inflammatory disorders." (PMID 31552186, 2019).
cervical cancer (1 paper, 2023). A primary or metastatic malignant neoplasm involving the cervix. "In our study, MIEN1 expression was negatively correlated with radioresistance, possibly because our research subjects had cervical cancer treated with radiotherapy, and the expression of MIEN1 may change after radiotherapy." (PMID 38028542, 2023). "We assessed the expression of WT1, AGT, MIEN1 and SPOUTY4 across cervical cancer tissues via IHC." (PMID 38028542, 2023).
colon cancer (1 paper, 2021). "Another study done on colon cancer reported that miR-136 suppressed the epithelial-to-mesenchymal transition of cancer cells by targeting the migration and invasion enhancer 1 (MIEN1) gene." (PMID 33562573, 2021).
endometriosis (1 paper, 2024). The growth of functional endometrial tissue in anatomic sites outside the uterine body. "Additionally, our study highlights several potential key genes likely involved in the pathogenesis of endometriosis by altering cell migration, such as DKK1, GRB7, MIEN1, PIK3R1, and KRT19." (PMID 39595577, 2024).
lymph node metastasis (1 paper, 2023). "The expression of MIEN1 was related to age, differentiation degree and lymph node metastasis." (PMID 38028542, 2023).
oral cancers (1 paper, 2018). "We and others have previously shown that MIEN1 is an oncogene involved in the migration, invasion and progression of breast, prostate and oral cancers and is associated with decreased overall survival." (PMID 30286132, 2018).
ovarian serous cystadenocarcinoma (1 paper, 2020). A malignant serous cystic epithelial neoplasm arising from the ovary. "Besides, according to the “Ovarian Serous Cystadenocarcinoma (TCGA)” study and using the tools from cBioportal, up-regulation of MIEN1, TGM2 or ZN428 in samples from these patients is correlated to poorer survival outcomes." (PMID 32867128, 2020).
ovarian tumor (1 paper, 2020). "In the library prepared from ovarian tumor tissue, 5 clones with coding sequences were identified using the HMGB1 bait (C1QA, DAG1, RPL29, RSF1, TGM2), and 6 (COMMD1, MIEN1, PCBP1, TBC1D25, ZFR, ZNF428) were identified with the HMGB2 bait." (PMID 32867128, 2020).
cancer (31 papers, 2010 to 2025). A tumor composed of atypical neoplastic, often pleomorphic cells that invade other tissues. "MIEN1 and Annexin A2 have been implicated in cancer progression and metastasis, but their modulation can also dampen inflammatory responses, suggesting potential for integrated sepsis and cancer therapies." (PMID 40563999, 2025). "Migration and invasion enhancer 1 (MIEN1) is a membrane associated protein overexpressed in various human cancers." (PMID 31552186, 2019). "Effect of loss/gain of MIEN1 protein and its effects on metastasis and invasiveness in different cancer." (PMID 31552186, 2019). "Findings from this study corroborated with TCGA dataset, revealing a positive association of MIEN1 expression with intermediate/high-grade cancer, low survival rate and smoking habit." (PMID 31552186, 2019). "MIEN1 overexpression was associated with cancer aggressiveness and CRC metastasis more frequently in the lymph nodes." (PMID 31552186, 2019). "Prenylated MIEN1 then translocates to the inner leaflet of the plasma membrane and potentiates filopodia formation whereas prenylation-deficient MIEN1-mutants fail to migrate, invade and display reduced metastatic capacity in cancer mouse models." (PMID 26272794, 2015). "In general, MIEN1 specific antibodies might have therapeutic potential in cancer treatment by suppressing important functions of MIEN1 or its associated proteins." (PMID 31552186, 2019). "Finally, MIEN1, located in the chromosomal region 17q12-21, was recently discovered and has been associated with enhanced migration in several types of cancer." (PMID 28832682, 2017). "We next hypothesized that the loss of methylation of the SINE Alu repeat in the MIEN1 promoter potentially results in higher expression of MIEN1 in cancer compared to normal cells." (PMID 27589566, 2016). "Post-translationally modified MIEN1 interacts with Syk kinase and Annexin A2 protein; polymerizes G-actin and stabilizes F-actin filament; induces focal adhesion kinase phosphorylation and decrease cofilin phosphorylation implicated in both invasion and metastasis of different cancer types." (PMID 31552186, 2019). "We have identified short peptides derived from the ITAM and prenylation motifs of MIEN1 as potential ACPs for cancer therapy." (PMID 38272230, 2024). "This approach has also been applied to design anti-cancer peptides from proteins like MIEN1 and Annexin A2, which are specific to cancer cells." (PMID 39590524, 2024). "In summary, our findings mark the first report of short peptides based on MIEN1 protein sequence capable of inhibiting cancer signaling pathways, effectively impeding cancer progression both in vitro and in vivo." (PMID 38272230, 2024). "initially showed the significance of migration and invasion enhancer 1 (MIEN1), formerly known as C17orf37, in promoting cancer cell migration and invasion via nuclear factor kappa B (NF-κB) pathway activation." (PMID 38272230, 2024). "Migration and invasion enhancer 1 (MIEN1) overexpression characterizes several cancers and facilitates cancer cell migration and invasion." (PMID 38272230, 2024). "MIEN1 is a membrane‐anchored protein that has an important influence on the migration and invasion of cancer cells, and higher MIEN1 levels are more related to cisplatin drug resistance in OC." (PMID 37525498, 2023). "MIEN1 is a primary regulator of tumor cell migration and invasion that is widely expressed as a membrane-fixed protein in various cancers." (PMID 38028542, 2023). "With respect to genes CDK12 (CRKRS), CWC25 (CCDC49), GRB7, MIEN1 (C17orf37), PNMT and SIRT3, they have been shown to be linked to HER2 receptor and cancer." (PMID 37096121, 2023). "In this review, we discuss the structure, function, expression and involvement of MIEN1 in cancer progression." (PMID 31552186, 2019).